ELOVL3 (ELOVL fatty acid elongase 3)
Description:
Catalyzes the first and rate-limiting reaction of the four reactions that constitute the long-chain fatty acids elongation cycle. This endoplasmic reticulum-bound enzymatic process allows the addition of 2 carbons to the chain of long- and very long-chain fatty acids (VLCFAs) per cycle. Condensing enzyme that exhibits activity toward saturated and unsaturated acyl-CoA substrates with higher activity toward C18 acyl-CoAs, especially C18:0 acyl-CoAs. May participate in the production of saturated and monounsaturated VLCFAs of different chain lengths that are involved in multiple biological processes as precursors of membrane lipids and lipid mediators.
Synonyms: CIG30; CIG-30
Tractability: Small molecule: a high-quality ligand is known; it belongs to a druggable protein family. Antibody: UniProt predicts a signal peptide or a membrane-spanning region. PROTAC: a small molecule that binds it is known.
Target class: Enzyme; Transferase
Gene: Protein-coding gene on chromosome 10 (102,226,299 to 102,229,589, forward strand). Ensembl gene ENSG00000119915.
Subcellular location: Endoplasmic reticulum membrane
Subcellular location (Human Protein Atlas): Cytosol; Vesicles
Pathways (Reactome):
Metabolism: Linoleic acid (LA) metabolism; Synthesis of very long-chain fatty acyl-CoAs; alpha-linolenic acid (ALA) metabolism
Circadian clock: RORA,B,C and NR1D1 (REV-ERBA) regulate gene expression
Developmental Biology: Transcriptional regulation of brown and beige adipocyte differentiation by EBF2
Gene Ontology:
Molecular function: fatty acid elongase activity; protein binding
Biological process: fatty acid elongation, monounsaturated fatty acid; fatty acid elongation, polyunsaturated fatty acid; fatty acid elongation, saturated fatty acid; very long-chain fatty acid biosynthetic process; alpha-linolenic acid metabolic process; linoleic acid metabolic process; long-chain fatty-acyl-CoA biosynthetic process; positive regulation of cold-induced thermogenesis; sphingolipid biosynthetic process; fatty acid elongation; unsaturated fatty acid biosynthetic process
Cellular component: endoplasmic reticulum; endoplasmic reticulum membrane; membrane
Genetic constraint (gnomAD): Loss-of-function variants: 10 observed, 14.96 expected, observed/expected ratio (o/e) 0.67, 90% interval 0.41 to 1.13. The upper end of that interval is the gene's LOEUF score, 1.13, which puts it in group 4 of 6, group 1 being the genes least tolerant of losing a copy. Missense variants: 274 observed, 354.07 expected, observed/expected ratio (o/e) 0.77, 90% interval 0.7 to 0.86. Synonymous variants: 116 observed, 130.63 expected, observed/expected ratio (o/e) 0.89, 90% interval 0.76 to 1.04.
Homologues: Orthologues: chimpanzee ELOVL3 (97% identical), macaque ELOVL3 (93% identical), dog ELOVL3 (80% identical), pig ELOVL3 (79% identical), rabbit ELOVL3 (79% identical), guinea pig ELOVL3 (77% identical), rat Elovl3 (72% identical), mouse Elovl3 (69% identical), tropical clawed frog elovl3 (50% identical), zebrafish elovl6l (44% identical), zebrafish zgc:92749 (43% identical), Drosophila melanogaster Baldspot (40% identical), and 3 more. Paralogues in human: ELOVL6 (44% identical), ELOVL4 (26% identical), ELOVL1 (26% identical), ELOVL2 (24% identical), ELOVL5 (24% identical), ELOVL7 (23% identical).
Diseases named in the same sentence as ELOVL3 in open-access papers:
ELOVL3 is named in the same sentence as 25 diseases in open-access papers, as found by Europe PMC text mining. Sharing a sentence is not in itself a finding about the gene and the disease. The quoted sentences say what the papers report.
Obesity (12 papers, 2012 to 2026). Accumulation of substantial excess body fat. "Transcriptome data suggest that testosterone deficiency contributes to the presence of ELOVL3 in obesity." (PMID 39123669, 2024). "Ablation of Elovl3 in mice causes resistance to diet-induced obesity, and reduces hepatic lipogenic gene expression and triglyceride content." (PMID 24551121, 2014). "Therefore, we aimed to explore the mechanism underlying obesity caused by testosterone deficiency and the relationship between ELOVL3 expression and fat deposition." (PMID 39123669, 2024). "Interestingly, diet restriction affected fatty acid synthesis genes the most, including Elovl3 (0.2% of control) – a gene positively associated with diet-induced obesity." (PMID 24551121, 2014). "Rutin has been shown to protect mice from HFD-induced obesity and adipocyte hypertrophy, and to up-regulate the transcription of genes (deiodinase 2 (Dio2), Elovl3, PGC-1α, UCPs) involved in energy expenditure in BAT and to maintain glucose sensitivity." (PMID 31346342, 2019). "Alterations in BAT thermogenesis were confirmed by elevated and decreased Uncoupling Protein 1 (Ucp1) and ELOVL Fatty Acid Elongase 3 (Elovl3) mRNA expression during cold or diet-induced obesity (DIO), respectively." (PMID 30190464, 2018). "In accordance, the mice lacking ELOVL3 (Elovl3−/−) developed by Zach-Avec and coworkers were resistant to the induction of obesity by an HFD, which was associated with a reduced FAs uptake and inhibited de novo synthesis." (PMID 38919749, 2024). "The results from the present study support a role for Elovl3 in diet-induced obesity." (PMID 24551121, 2014). "A SNP in ELOVL3 showed potential association with both type 2 diabetes, fasting plasma glucose and waist circumference while two SNPs in ACP1 and SLC27A4 were selected from analyses of obesity, BMI and waist circumference." (PMID 23160641, 2013). "We discovered that the expression levels of ELOVL3, ELOVL5 and ELOVL6 increased similarly to estimated elongase activity (P<0.05), while the mRNA expression level of ELOVL1 decreased during the first year after obesity surgery (P=6 × 10−5)." (PMID 28869586, 2017). "Moreover, induction of obesity by high-fat diet feeding markedly altered the expression of each examined isoform of ELOVL, namely ELOVL1, ELOVL3, and ELOVL6 (+ 65.04%, + 36.19%, − 37.34% and + 65.81%, vs. the control group, respectively, p < 0.05) in the white skeletal tissue." (PMID 36879113, 2023).
psoriasis (4 papers, 2020 to 2024). An autoimmune condition characterized by red, well-delineated plaques with silvery scales that are usually on the extensor surfaces and scalp. "ELOVL3 (encoding elongation of very-long-chain fatty acids) is involved in fatty acid metabolism and downregulated in psoriasis, a common extra-articular manifestation of AS." (PMID 37388915, 2023). "ELOVL3 was one of the most downregulated genes in psoriasis patients." (PMID 32316273, 2020). "A psoriasis mouse model showed decreases in the expression of fatty acid elongases ELOVL1, ELOVL3, and ELOVL4 as well as ceramide synthase 3, which are all involved in the synthesis of ceramides exceeding 24 carbons." (PMID 38992724, 2024). "The upregulation of genes such as ELOVL3 and PECR in non‐lesional skin and ELOVL3 and FADS2 in plaque skin may improve lipid barrier function, suggesting that bevacizumab could potentially alleviate epidermal barrier dysfunction and limit disease progression in psoriasis." (PMID 39624732, 2024).
prostate carcinoma (3 papers, 2021 to 2023). A carcinoma that arises from epithelial cells of the prostate gland. "Among other five TRGs, TUBB4A serves as a tumor-promoting factor in several tumor types including melanoma and prostate cancer, and ELOVL3 is considered as a risk gene in hepatocellular carcinoma." (PMID 37976136, 2023). "BRG1, a chromatin remodeling protein, activates ELOVL3 transcription, thereby stimulating migrative/invasive properties of prostate cancer cells." (PMID 38186579, 2023). "A small number of studies have shown that ELOVL3 is highly expressed in colorectal and prostate cancers." (PMID 34150630, 2021).
glioblastoma (2 papers, 2023). The most malignant astrocytic tumor (WHO grade IV). "According to the GEPIA portal, higher expression of Elovl3 is associated with a worse prognosis for glioblastoma patients, as is the case for Elovl1." (PMID 37046844, 2023). "Expression data for ELOVL1, ELOVL3, ELOVL6, SCD, and FADS2 were obtained from raw data published in our previous papers, where we examined the expression of elongases and desaturases in glioblastomas." (PMID 37239243, 2023). "The expression of Elovl3 does not change in glioblastoma tumors compared to the brain tissue without a tumor." (PMID 37046844, 2023).
hepatocellular carcinoma (2 papers, 2022 to 2023). A malignant tumor that arises from hepatocytes. "Upregulated expression of ELOVL3 was identified in hepatocellular carcinoma and colorectal cancer, which was a risk factor for these cancer patients." (PMID 36568396, 2022).
melanoma (2 papers, 2023 to 2025). A malignant, usually aggressive tumor composed of atypical, neoplastic melanocytes. "Yu Zhang and colleagues have demonstrated that high ELOVL3 expression is associated with reduced overall survival (OS) and disease-free survival (DFS) in HCC, and this effect may be comparable in melanoma." (PMID 41465101, 2025).
adrenal tumors (1 paper, 2022). "They assessed in the perirenal region of PPGL higher expression of UCP1, CIDEA, ELOVL3, EBF3, FBXO31 and LHX8, but not TNFSRF9, TBX1 or TMEM26, in comparison with seven subjects with non-functional adrenal tumors." (PMID 35327387, 2022).
atherosclerosis (1 paper, 2024). A disease characterized by the build-up of fatty material and calcium deposition in the arterial wall resulting in partial or complete occlusion of the arterial lumen. "Elovl3 (participating in the production of saturated and monounsaturated very long-chain fatty acids) was downregulated by the drug PX-478, thereby also reducing atherosclerosis." (PMID 38469142, 2024).
atopic dermatitis (1 paper, 2018). "Some of lipid metabolic genes discovered in our analysis were also reported as declined genes in patients with psoriatic (ACSBG1, ALOX15B, ELOVL3, FADS1, FADS2, and THRSP) or atopic dermatitis (CYP4F8, ELOVL3, FADS1, FADS2, FAR2, and HAO2)." (PMID 30021930, 2018).
colitis (1 paper, 2021). Inflammation of the colon. "DSS-induced colitis mice showed significantly decreased expressions of PPARα, PGC-1α, and thermogenic genes including ND5, Prdm16, Cidea, Elovl3, Dio2, and UCP1 both in SAT and BAT compared to non-colitis control mice." (PMID 33674694, 2021).
dermatitis (1 paper, 2019). An inflammatory process affecting the skin. "The expression of ELOVL4 substantially decreased by 76.2 ± 9.6% in FAg-induced dermatitis compared with that in control mouse skin, and the expression of the other ELOVL isozymes except for ELOVL3 also significantly decreased, with the highest inhibition in ELOVL6." (PMID 30838224, 2019).
dry eye (1 paper, 2025). "Previously, changes in MG lipidomes induced by inactivation of critical genes of meibogenesis, such as Elovl3, Soat1, Awat2, Sdr16c5/Sdr16c6, and others were shown to cause MG dysfunction (MGD) and dry eye in experimental animals." (PMID 41373590, 2025).
glioma (1 paper, 2022). A benign or malignant brain and spinal cord tumor that arises from glial cells (astrocytes, oligodendrocytes, ependymal cells). "Additionally, a higher expression of ELOVL3 in glioma is associated with a worse prognosis, and for ELOVL1, it is associated with a tendency toward a worse prognosis (p = 0.066)." (PMID 36291290, 2022).
HCMV infection (1 paper, 2013). "To confirm the transcript results, we analyzed the protein levels of two of the siRNA hits, ACSL1 and ELOVL3, during HCMV infection and found that both proteins were elevated." (PMID 23696731, 2013).
insulin-resistant (1 paper, 2024). "Noteworthy, the herein study has shown that treatment of obese and insulin-resistant rats with CBG caused a pronounced decrease in either ELOVL3 or ELOVL6 intramuscular expression." (PMID 38919749, 2024).
liver cancer (1 paper, 2022). An epithelial or non-epithelial malignant neoplasm that arises from the liver. "In liver cancer, ELOVL1 and ELOVL3 were strongly associated with poor prognosis of HCC by survival analysis and differential expression analysis." (PMID 35912257, 2022). "Among the ELOVLs family, only ELVOL1 and ELOVL3 might have an impact on the survival of liver cancer patients." (PMID 35912257, 2022).
metabolic syndrome (1 paper, 2019). A cluster of metabolic risk factors for CARDIOVASCULAR DISEASES and TYPE 2 DIABETES MELLITUS. "Importantly, both low-dose and high dose of L-arabinose further decreased mRNA level of Elovl3, suggesting that the alleviation of HFD-induced metabolic syndrome by L-arabinose might be mediated by suppressing long-chain fatty acid synthesis in liver." (PMID 31847305, 2019).
ovarian carcinoma (1 paper, 2021). A malignant neoplasm originating from the surface ovarian epithelium. "We suggest that ELOVL3 expression may also be involved in ovarian cancer occurrence and progression by inducing lipid metabolism reprogramming." (PMID 33278864, 2021).
tumor (6 papers, 2021 to 2023). "Elevated expression of ELOVL1 and ELOVL3 in this tumor type is associated with a poorer prognosis." (PMID 37239243, 2023). "There was a negative correlation in the ELOVL2 expression in the enhancing tumor region with the ELOVL3 expression in the tumor core." (PMID 36291290, 2022). "The expression levels of TMEM44, TMEM67, CBX3, and ELOVL3 in tumor tissue were higher than in normal tissue, which was consistent with the trend in EC." (PMID 33463006, 2021). "Additionally, the ELOVL3 expression in the tumor core was positively correlated with the ELOVL5 expression from the enhancing tumor region and negatively correlated with the ELOVL2 expression from the enhancing tumor region." (PMID 36291290, 2022). "The ELOVL3 expression in the tumor core was negatively correlated with ELOVL5 and ELOVL6 expressions in the enhancing tumor region." (PMID 36291290, 2022). "This study examines the expression of elongases ELOVL1, ELOVL2, ELOVL3, ELOVL4, ELOVL5, ELOVL6, and ELOVL7 in GBM tumor samples from 28 patients (16 men and 12 women), using a quantitative real-time polymerase chain reaction (qRT-PCR)." (PMID 36291290, 2022). "The ELOVL3 expression in the same region of the GBM was not correlated with other elongases except for the ELOVL2 expression in the enhancing tumor region." (PMID 36291290, 2022). "And the expression levels of MORC2, ELOVL3 and ENO3 were significantly increased in tumor tissues." (PMID 36568396, 2022). "The ELOVL3 expression was not different in the GBM tumor core relative to the peritumoral area in both the women and men (p > 0.05)." (PMID 36291290, 2022). "There was a negative correlation between the ELOVL3 expression in the tumor core and BMI." (PMID 36291290, 2022). "In the tumor core, the expression of ELOVL3 had a negative correlation with body weight and BMI, while in the peritumoral area, there was a negative correlation between the ELOVL2 expression and height and a negative correlation between the ELOVL4 expression and cigarette pack-years." (PMID 36291290, 2022).
cancer (3 papers, 2021 to 2022). A tumor composed of atypical neoplastic, often pleomorphic cells that invade other tissues. "Previous studies have shown that ELOVL3 could predict the prognosis of cancers." (PMID 36189312, 2022).
ELOVL3 also shares sentences with these, for which no sentence is quoted: colorectal cancer (1 paper); diabetes (1); hyperlipidemia (1); liver fibrosis (1); type 2 diabetes (1).